TNF (tumor necrosis factor)
Diseases named in the same sentence as TNF in open-access papers (continued):
Sharing a sentence is not in itself a finding about the gene and the disease.
infection (continued). "Mechanism of EGCG as an anti-infection by L-pneumophila bacteria due to nicotine is through macrophages that produce tumor necrosis factor alpha (TNF-α) and interferon gamma (IFN-γ)." (PMID 37346971, 2023). "Upregulation of AAT occurs in response to infection and tissue injury, in order to promote tissue repair, in a mechanism driven by interleukin-6 (IL-6) and tumor necrosis factor (TNF)." (PMID 36983294, 2023). "ELISA of culture supernatants revealed that Kpn infection induced high levels of IL-6 and TNF-α secretion in MH-S cells at 2 h post infection: 17.09 and 14.40 pg/mL, respectively (p < 0.05)." (PMID 37958922, 2023). "It is one of the core genes of inflammation and infection prevention that can participate in the occurrence of COPD by regulating TNF-α and IL-17." (PMID 37056763, 2023). "Activated macrophages produce inflammatory mediators such as NO, TNF-α, and IL-6, and increase the inflammatory response at the early stage of infection." (PMID 36768389, 2023). "To investigate the role of TNFα signaling in NK cell activation, we utilized an in vivo model of acute infection by challenging C57BL/6 (B6) mice with MCMV." (PMID 37553427, 2023). "In young animals, TNF-α peaked at higher levels and started to decrease when IL-10 peak expression was achieved on the ninth day of infection; alternatively, in adults, TNF-α expression started to decrease before IL-10 peaked." (PMID 36839438, 2023). "In comparison, in influenza (genus Influenza A/B/C/D) infection, the cytokines IL-1β, IL-4, IL-5, IL-6, IL-10, IL-12, IL-13, TNF-α, and IFN-γ are relevant to immune cell interaction in figures." (PMID 36851285, 2023). "Overexpressed immune genes in response to infection included several Toll-like receptors, TNF and NF-κB immune signaling genes, and the antimicrobial peptide Big defensin ApBD1." (PMID 36936911, 2023). "On the other hand, TNF-alpha progressively increased for both strains during the post-infection measurements." (PMID 38075868, 2023). "We also observed that bacterial replication was inhibited completely in both Tnf−/− and WT BMDMs that were treated overnight with recombinant murine TNF (rTNF) prior to infection." (PMID 37461589, 2023). "Although CQ treatment increased the number of TNF-producing macrophages, it reduced the levels of TNF and increased the levels of IL-10 production by these cells during infection." (PMID 38256880, 2023). "Studies reported that serum TNFα was the first elevated cytokine due to LI infection, followed by the gradual increase in the secretion of IFN-γ and IL-6, while the serum concentrations of IL-10, IL-4, and TGFβ decreased." (PMID 37372164, 2023). "In any case, TNF plays an important role in the host’s response to infection, by maintaining the integrity of the granuloma that forms as a result of the infection." (PMID 38222154, 2023). "With the E. faecalis 36 clinical isolate, infection induced statistically significant IL-6 and TNF-α levels similar to that secreted in response to UTI89." (PMID 37051302, 2023). "IL-6 and TNF-α are typical pleiotropic cytokines produced in response to tissue damage and infection." (PMID 37630849, 2023). "In vivo, whole body exposure to PM10 vs. control air exposed mouse corneas showed early perforation and/or corneal thinning at 3 days post infection, accompanied by increased TNF-α and decreased SOD2 protein levels." (PMID 37868351, 2023). "IL6 and TNF-α are proinflammatory factors, and previous studies have revealed that IL6 and TNF-α levels are increased during infection or tissue damage, and their low expression levels are of great significance to DF wound healing." (PMID 36670362, 2023). "In the lungs, levels of the proinflammatory cytokine TNFα were actually further elevated after H7N7 infection in both young and older mice previously vaccinated." (PMID 37063291, 2023).
infection (continued). "In the immune system, TNF-α needs to bind to TNF receptors (TNFRs) to initiate the inflammatory reactions for effective host defenses against pathogen infection." (PMID 38203454, 2023). "In the CT-P10 infection group, the differentially expressed genes were enriched in pathways such as the TNF signaling pathway, IL-17 signaling pathway, and apoptosis at all three time points post-infection." (PMID 37515115, 2023). "During inflammation, there is the recruitment of immune cells at the infection site, which are the target of the infection, and the production of cytokines, such as TNF and IL-1a, responsible for the disruption of epithelial barrier integrity." (PMID 36798134, 2023). "Increased expression of TNF-α in splenic mononuclear cells occurred soon after infection, both in young and adult animals." (PMID 36839438, 2023). "At the stage of severe infection and inflammation, macrophages first polarized to M1 phenotype by producing TNF-α, IL-1β, IL-12, and IL-23 against the stimulus l." (PMID 37065141, 2023). "As a pro-inflammatory cytokine, TNF-a is expressed at an early stage of infection in fish and has a key role in regulating inflammation." (PMID 38068937, 2023). "As a result, the secretion of cytokines decreases, such as tumor necrosis factor (TNF) and interleukin-12 (IL-12), which are needed to control infection." (PMID 37113130, 2023). "A previous study found that the inflammation-related cytokine genes IL-1β, IFN-α, TNF-α and NF-κB in the blood had a higher over-expression after infection with C. perfringens type C." (PMID 36975519, 2023). "Studies have shown increased levels of TNF, IL-1β, 4, 6, 7, 8, 10, and 15 two months after the infection, and increased levels of IL-1β, six and TNF-α eight months later." (PMID 37894116, 2023). "Zi-treated mice showed reduced inflammatory scores in the lungs, reduced dendritic cell-producing tumor necrosis factor (TNF), and increased neutrophil-producing interleukin (IL)-10 in the lungs 3 days after infection (dpi), the peak of lung damage." (PMID 37896826, 2023). "Infection and cytokines (e.g., IL-1/2/6, TNFα) by affecting hormone release from Hypothalamus, Pituitary and Adrenal glands activate maternal and/or fetal HPA axis leading to release of glucocorticoids (GCs) as an end product." (PMID 37700750, 2023). "Of note, the maximal degree of phosphorylation was obtained in both cell lines at later times after infection with the ATCC strain (60 min) with respect to TNF treatment (30 min) (B for comparison)." (PMID 37894827, 2023). "Stress, such as trauma and infection, induces the production of inflammatory cytokines and TNFα, which promote muscle catabolism." (PMID 37629468, 2023). "TNF-α, IL-1β, and IL-6 levels showed a significant positive correlation with the severity of infection (r = 0.660, 0.539, and 0.495, respectively)." (PMID 37068081, 2023). "A study of the reaction in infection with Mycobacterium tuberculosis postulates that IFN-γ increases the expression of TNF-α and the IL-18 receptor in uninfected macrophages and the presence of the infectious agent at 4 h of treatment." (PMID 38140192, 2023). "Levels of IL-6, TNFα, IL-10, and other cytokines are significantly increased with infection; elevation of IL-6 and IL-10 is a reliable indicator of a more severe disease." (PMID 36771194, 2023). "The present study has described the possible value of the IL-1 and TNF- α driven PTX3 as a CSF biomarker for infections in the CNS." (PMID 36862691, 2023). "TNF-α was also significantly higher in WT mice following P. aeruginosa single-species infection compared to CF mice (***P<0.001)." (PMID 36748431, 2023). "Multiple meta-analyses have also revealed that TNF gene polymorphisms are associated with H1N1 virus susceptibility and severity of infection." (PMID 37228892, 2023).
infection (continued). "By performing H&E staining and ELISA at 7 days post-infection (dpi), we found that Sept2fl/flLyz2-Cre mice showed more severe inflammation in the lungs and higher cytokine levels of TNF-α, IL-1β, IL-6 and IL-12 p40 in the BALF than control mice." (PMID 37978190, 2023). "COs and BVOs also expressed IL1β and TNFα after infection, but the expression levels were lower than fCBOs." (PMID 36697403, 2023). "While IL-6, IRF4, IRF6, and CXCL2 were significantly unchanged, TNF-α was significantly elevated in the infection-derived EVs at both 48 h and 72 h when compared to the control-derived EVs (* p = 0.01 and * p = 0.02, respectively) (respectively)." (PMID 36979955, 2023). "Looking closer at the compound andrographolide, in in vivo experiments, this compound reduced the increase in TNF-α and IL-6 that followed infection of the lungs with S. aureus, while keeping them high enough to adequately manage the infection." (PMID 37765014, 2023). "In response to infection, neutrophils are recruited to the lungs depending on the cytokine signaling pathways of IL-6, nuclear factor kappa B, and tumor necrosis factor." (PMID 36910136, 2023). "After antigen presentation and activation by dendritic cells (DCs), CD4+ and CD8+ T lymphocytes increase their production of pro-inflammatory Th1-type cytokines, such as IFN-γ, TNF and IL-2, to try to resolve the infection." (PMID 38106411, 2023). "We have shown previously, in our combined in vitro and in vivo study, that THP-1 cells infected with live and heat-killed T. forsythia were the most potent inducers of IL-1β and TNF compared to polymicrobial infection." (PMID 38003583, 2023). "When IL-1β is released in response to infection or tissue damage, it activates other cytokines production, for instance, TNFα and IL-6." (PMID 38068877, 2023). "It is important to detect MDA5-mediated TNF expression in the early stage of infection with high viral titer (MOI = 3 for 18 h) to ensure that MDA5 rapidly senses viral dsRNA and then activates the NF-κB pathway." (PMID 37956198, 2023). "IAVTNF-α demonstrated significantly higher levels of IL-6, IL-1β, IL-8, IFN-γ, and TNF-α in comparison to IAVQUI after 24 h infection." (PMID 37163429, 2023). "The results demonstrated that Evans blue, TNF-α and IL-1β levels were significantly increased in the infection groups compared to the control group." (PMID 36341547, 2023). "Granuloma formation, mediated by proinflammatory cytokine TNF-α, helps contain the infection and limit bacterial dissemination." (PMID 37513768, 2023). "In these experimental conditions, a non-significant but reproducible reduction in bacterial internalization rate of approximately 40% was observed in MPI treated with cytochalasin D leading to a significant decrease in TNF secretion after infection." (PMID 37841236, 2023). "Pro-inflammatory cytokines (IL-6, IFNγ, TNFα, and IL-12p40) as well as the anti-inflammatory cytokine IL-13 increased, whereas release of IL-1Ra (an IL-1β inhibitor) was reduced by infection with the mutant strain." (PMID 37669276, 2023). "During the infection period, we observed significant increases in fecal water content, D-LA, TNF-α, and malondialdehyde concentrations (p < 0.05)." (PMID 37508014, 2023). "The cytokine TNF-α, as a proinflammatory cytokine, is produced soon after infection and promotes the acute inflammatory reaction." (PMID 37125939, 2023). "The body is prompted to release proinflammatory cytokines such as TNF-α when the skin is injured and an infection develops." (PMID 37310979, 2023). "In contrast to amniotic fluid, IFN‐β, IL‐10, IL‐6, and IL‐27 levels were undetectable in response to infection, and TNF‐α levels were decreased albeit barely above the limit of detection." (PMID 37259639, 2023). "The numbers of multifunctional cytokine+ CD4 T cell that produced IFN‐γ, IL‐2 and TNF were particularly stable between days 9 and 30 post‐infection." (PMID 37490492, 2023).
infection (continued). "Other inflammatory mediators, such as interleukin (IL)-1β, IL-6, tumor necrosis factor (TNF)-α and IL-8 have also been found to be elevated in response to infection." (PMID 37317134, 2023). "Following infection, the proinflammatory cytokines IL-1β, TNFα, and IL-6 were upregulated in the olfactory bulb and hippocampus at DPI-4." (PMID 38006064, 2023). "This is in line with a previous study that reported synergistic effects between organic acids in the prevention of intestinal inflammation by lowering the production of IL-6 and TNF-α after infection with enterohemorrhagic Escherichia coli in mice." (PMID 37007531, 2023). "Although EHEC O157:H7 infection elevates the secretion of TNFα, infection by EHEC O157:H7 can also reduce the activation of NF-κβ; however, the mechanism is not fully understood." (PMID 37627368, 2023). "For instance, activated NF-κB translocates to the nucleus, stimulating the secretion of inflammatory factors such as IL-1β, TNF-α, and IL-6, thus aggravating the inflammatory response after infection." (PMID 36979335, 2023). "Consistent with the results of in vitro studies, Del2R infection induced higher levels of IL-1β and TNF-α production with significantly reduced replication in pigs compared with ASFV-WT infection." (PMID 37566637, 2023). "We then sought to dissect which downstream pathways are engaged by caspase-8 in TNF-primed BMDMs to mediate cell death following infection." (PMID 37279255, 2023). "Similar findings have been illustrated in models of T. cruzi infection, where transgenic mice capable of neutralizing TNFα have increased infection severity and higher mortality rates compared to wild-type mice." (PMID 37375100, 2023). "In infections with regular vegetative cells, the IL-6 and TNF-α inflammatory response continued to increase in the first 1.5 h, remaining constant at 24 h, while CXCL-8 decreased by 24 h." (PMID 36920189, 2023). "The present investigation revealed that infection with T. canis resulted in a significant increase in the levels of TNF-α inside the brain tissues of the infected mic." (PMID 37874393, 2023). "TNF has been described to have dual roles in infection—some TNF is critically important for Mtb control in experimental models and in clinical studies, but too much TNF drives macrophage necrosis and release of bacteria to infect new cells." (PMID 37439558, 2023). "In resolved mice, UPEC initially form intracellular bacterial communities in the superficial facet cells, similar to that in adult naïve mice, but they are rapidly shed within the first 6 h of infection via enhanced TNFα-mediated inflammation." (PMID 37037942, 2023). "TNF is a pleiotropic cytokine involved in inflammatory conditions and host defense against infection." (PMID 37327341, 2023). "Although increased production of pro-inflammatory cytokines, such as TNF-α, is helpful in boosting clearance of invasive infections and phagocytosis of cell debris, prolonged inflammatory processes can cause harmful brain damage and neurodegeneration." (PMID 37874393, 2023). "In the supernatant of C. burnetii infected human macrophages, we observed the highest amount of TNFα at 24 h post-infection." (PMID 36793725, 2023). "In the CSF of newly-weaned hamsters, TNF-α concentrations were increased at 4 dpi after Omicron BA.2 infection." (PMID 37122119, 2023). "This study showed that PbA-infected mice exhibited an increase in TNF-α, IL-1β, and IL-6 expression levels in the brain at day 13 post-infection." (PMID 37730604, 2023). "Next, we assessed polyfunctionality of vaccine-induced SARS-CoV-2-specific CD4+ T cells, as multifunctional Th1 cells (IFN-γ+TNF-α+IL-2+) have been described to provide a better correlate of immune protection against infection after vaccination." (PMID 37199415, 2023).
infection (continued). "It has been proven that a chronic biofilm infection is related to a permanent and lower-grade host inflammatory response (lower levels of IL-1β and TNF expression) when compared with an infection of acute wounds." (PMID 37760822, 2023). "IL-1β, IL-6, and TNF-α mRNA expressions were significantly induced 12 h after infection with B1033, and when complemented with fadD33, these mRNA expressions reverted to those observed in the wild-type BCG strain." (PMID 37998345, 2023). "Our study has shown that infection with the attenuated recombinant Del2R induced high levels of IL-1β and TNF-α production in PAMs compared with infection with ASFV-WT." (PMID 37566637, 2023). "CRP is a plasma protein that is synthesized in the liver, induced by IL‐1, IL‐6, and TNF‐α, and considered a marker for inflammation, infection, and tissue injury." (PMID 36314077, 2023). "T cell-interacting, activating receptor on myeloid cells protein 1 is a triggering receptor on macrophages and neutrophils related to TNF-α and IL-8 production against pathogen infection." (PMID 37238072, 2023). "In the case of infection of human alveolar macrophages with Mycobacterium tuberculosis, apoptosis is induced by a TNF-α-dependent mechanism that represents a host defense strategy since it limits the growth of this intracellular pathogen." (PMID 38112844, 2023). "Serum levels of IFN-γ and TNF-α were measured from the serum samples to assess the extent of inflammation during the infection process." (PMID 37954132, 2023). "Intriguingly, a subset of participants with pronounced tumor necrosis factor-alpha post-mock infection (Cluster 1) showed attenuated cytokine responses in contrast to their counterparts in Cluster 2 and Cluster 3 (all adjusted P < 0.05)." (PMID 37900310, 2023). "About 5–6 weeks post infection, schistosome induces Th1 dominant responses of the host with the upregulation of effector cytokines (such as TNF-α and IFN-γ)." (PMID 37276235, 2023). "Once activated, M1 macrophages will produce tumor necrosis factor-α (TNF-α), L-1β and oxygen free radicals to fight infection or remove foreign substances, thus terminating the damage repair process and preventing excessive repair." (PMID 37707713, 2023). "In a mouse model infected with Pseudomonas, the intrapulmonary levels of inflammatory cytokines (TNF-α, IL-1β, and IL-6) and neutrophils were the highest on day 3 of infection." (PMID 36982713, 2023). "On days 5 and 15 PI, TBX2 mRNA expressions and the levels of IFN-γ and TNF-α in serum were significantly increased after the infection compared to the control group." (PMID 37593762, 2023). "In this study, we developed a Th1 environment in the T. crassiceps cysticerci model with resistant C57BL/6 mice, which is confirmed by the sustained increase in IL-12, INF-γ, and TNF and a low parasitic load during 8 weeks of infection." (PMID 37242348, 2023). "We observed a substantial increase in the level of caspase-11 protein in TNF-primed cellular lysates prior to L. pneumophila infection, suggesting that TNF licenses cells to react more rapidly to infection by upregulating caspase-11 levels." (PMID 37279255, 2023). "The IFN-γ in turn activates macrophages that induce TNF-α secretion for infection containment and mycobacterial growth restriction." (PMID 36646786, 2023). "The production of SAA by macrophages was confirmed upon direct administration of TNFα to macrophages and during aerosol infection with M. tuberculosis." (PMID 37153579, 2023). "The results show that CATH-1 significantly reduced the secretion of IL-6 and TNF-α at 2 h post-infection (hpi) when CATH-1 was co-incubated with SS2." (PMID 37605242, 2023). "perfringens infection, as evidenced by mucosal erosions, goblet cell reduction, immune cell infiltration and increased levels of the proinflammatory cytokine TNF-α, when compared with pfoA−-infected animals." (PMID 37231089, 2023).